WNT5A (Wnt family member 5A)
Diseases named in the same sentence as WNT5A in open-access papers (continued):
Sharing a sentence is not in itself a finding about the gene and the disease.
melanoma (continued). "Prolonged treatment with BRAF inhibitors induces WNT-5A expression in melanoma cells and contributes to the development of resistance to BRAF inhibitor-induced apoptosis." (PMID 26514730, 2016). "In melanoma, Wnt5a activated the Wnt/Ca2+ pathway, leading to activated CDC42, cytoskeletal changes, and the rapid release of exosomes containing the immunomodulatory cytokine IL-6 and the proangiogenic factors IL-8, VEGF and MMP2." (PMID 27571105, 2016). "Similar to WNT5A, the pro-inflammatory cytokine IL-6 promotes melanoma cell invasion, and its increased expression is correlated with reduced overall patient survival." (PMID 27191257, 2016). "WNT-5A can also confer a survival advantage to melanoma cells, thereby negatively influencing the outcome of therapeutic approaches." (PMID 26514730, 2016). "In the next set of experiments, we employed a more feasible therapeutic approach by combining Box5 (a WNT5A antagonist) and a neutralising anti-IL-6 antibody to investigate the efficacy of such a combined treatment on melanoma cell migration and invasion." (PMID 27191257, 2016). "Apart from WNT5A, there are other regulators of melanoma cell invasion that promote metastasis; IL-6 is one of these regulators." (PMID 27191257, 2016). "Wnt5a is involved in regulating melanoma cell orientation with respect to the surrounding tissue, polarity, and directional movement in response to positional cues from chemokine gradients, through activating the small guanosine triphosphatases Rab4 and RhoB." (PMID 27571105, 2016). "We observed that knocking down Wnt5a in invasive melanoma cell lines increased SOCE, while conversely overexpression of Wnt5a in non-invasive cells diminished SOCE to levels recorded in invasive cells." (PMID 27417567, 2016). "Together, our observations provide evidence for the existence of an endogenous WNT5A-IL-6 positive feedback loop mechanism that facilitates the increased expression of these two pro-metastatic factors in WM852 melanoma cells." (PMID 27191257, 2016). "More importantly, we demonstrated that the IL-6-induced p38α-MAPK activation promoted melanoma cell migration and invasion through increased WNT5A expression." (PMID 27191257, 2016). "We previously showed that WNT5A signaling can trigger the PI3K-AKT pathway in melanoma cells, thereby driving the aerobic glycolysis." (PMID 26393652, 2015). "Pre-clinical studies suggest that some melanoma cell lines express very high amounts of the WNT5A protein." (PMID 26393652, 2015). "The focus of the current review will be on melanoma development, signaling pathways important to acquired resistance to BRAFi, and why WNT5A inhibitors are attractive candidates to be included in combinatorial therapies for melanoma." (PMID 26393652, 2015). "In melanoma, Wnt5a levels have been shown to correlate with tumor progression, but the function of Wnt5a in the initiation and progression of other cancers is much less clear." (PMID 26029828, 2015). "Intriguingly, it was recently reported that Wnt5a activates Arf6, leading to the disruption of N-cadherin/β-catenin complexes, and increased melanoma cell invasion." (PMID 25779663, 2015). "Although the proposal that Wnt5a increases cell migration is compatible with its capacity to increase Arf6 activity in melanoma cells, we have limited knowledge concerning regulation of Wnt5a expression by EGF/Arf6 signaling in gastric cancer cells." (PMID 25779663, 2015). "Our studies indicate that Mov10 shRNA increases expression of FASN and SCD in cultured melanoma cell lines promoting Wnt5a secretion." (PMID 26029828, 2015). "Reduction of Mov10 expression by short hairpin RNA (shRNA) increases the level of lipid modified and secreted Wnt5a in melanoma cell lines." (PMID 26029828, 2015). "Recently, it was established that IL-6, a pro-inflammatory cytokine, can up-regulate the expression of WNT5A in melanoma cells, in a p38α-MAPK dependent manner." (PMID 26393652, 2015).
melanoma (continued). "We as well as others have demonstrated that WNT5A protein levels in different melanoma cell lines are variable and that sometimes the levels are very high." (PMID 26393652, 2015). "In particular, Wnt5a/FZD2 signaling has been shown to control melanoma Ca2+ homeostasis, cellular migration, and invasion in colon cancer." (PMID 26132195, 2015). "It has been demonstrated that highly proliferative melanoma cells express high β-catenin and low WNT5A, while more invasive melanomas express high WNT5A and low β-catenin." (PMID 26393652, 2015). "Next, Mov10 expression was inhibited by shRNA in the moderate Wnt5a secreting melanoma cell line UACC903." (PMID 26029828, 2015). "Expression of the Wnt ligand Wnt5a is frequently elevated in melanoma and is thought to be a critical regulator of cell movement during metastasis." (PMID 26029828, 2015). "Mov10-FLAG was ectopically expressed in the high Wnt5a secreting melanoma cell lines FS5 and M93-047." (PMID 26029828, 2015). "Many research groups have reported WNT5A staining in clinical specimens in several tumor types, including melanoma." (PMID 26393652, 2015). "Our studies reveal a previously unreported role for Mov10 in regulating the Wnt5a signaling pathway during melanoma progression." (PMID 26029828, 2015). "Apart from the established role played by WNT5A in melanoma migration and metastasis, its role as a regulator of melanoma phenotype switching has also emerged." (PMID 26393652, 2015). "On the basis of our previous findings we strongly propose a positive feedback loop whereby WNT5A regulates its own expression by indirectly regulating IL-6 in melanoma cells." (PMID 26393652, 2015). "Proteomics screening revealed that WNT5A altered the expression of at least 174 different proteins in melanoma cell line and Box-5 inhibited the majority of these changes." (PMID 26393652, 2015). "WNT5A-mediated downregulation of LEF-1 (a transcriptional regulator of MITF) switches the melanoma cell phenotype from proliferative to invasive." (PMID 26393652, 2015). "Inhibition of Mov10 increases secreted Wnt5a levels in melanoma cells by increasing Wnt5a synthesis and acylation." (PMID 26029828, 2015). "In later studies, WNT5A mRNA expression was established as a robust marker of the metastatic melanoma phenotype." (PMID 26393652, 2015). "ROR1 and ROR2, receptors associated with WNT5A signaling, have also been implicated in WNT5A-induced phenotype switching, with ROR2 expressing melanoma cells demonstrating a more invasive phenotype." (PMID 26393652, 2015). "A similar trend was also reported in BRAFi-resistant melanoma tumors, where 7 of the 11 patients showed increased WNT5A expression compared to pretreated samples." (PMID 26393652, 2015). "WNT5A directs migration and invasion of melanoma cells in a PKC-dependent manner by inducing the expression of Slug, which induces EMT." (PMID 26393652, 2015). "Recent studies have shown that WNT5A plays a key role in enhancing the resistance of melanoma cells to BRAFi." (PMID 26393652, 2015). "Just as in the WNT5A induced malignant melanoma exosomes, Rab5b was expressed in plasma-derived exosomes from malignant melanoma patients." (PMID 24766647, 2014). "Wnt5a overexpression correlates significantly with the survival and the development of metastases in melanomas." (PMID 24944588, 2014). "Here we show that, in melanoma cells with low endogenous WNT5A expression, the stimulation with rWNT5A induces a rapid release of exosomes containing the immunomodulatory cytokine IL-6 and the pro-angiogenic factors IL-8, VEGF and MMP2." (PMID 24766647, 2014). "This has partly been described by the findings that WNT5A expression in melanoma cell lines increases migration and invasion." (PMID 24766647, 2014). "A hexapeptide Box5, derived from Wnt5a and stabilized by the N-butyloxycarbonyl group, has been developed to antagonize Wnt5a-stimulated metastasis in melanoma." (PMID 26056595, 2014).
melanoma (continued). "We first determined the basal expression levels of WNT5A protein in 5 malignant melanoma cell lines, Mewo, SKmel28, A2058, A375 and HTB63 (also known as HT-144)." (PMID 24766647, 2014). "High expression of WNT5A in melanoma tumors correlates to formation of distant metastasis and poor prognosis." (PMID 24766647, 2014). "To investigate the involvement of Cdc42 in the present WNT5A induced effects, we first confirmed that rWNT5A indeed activated Cdc42 also in malignant melanoma Mewo cells." (PMID 24766647, 2014). "While Wnt5a has been described as a tumor promoter in melanoma, gastric, pancreatic, and prostate cancers, it was suggested to be a tumor suppressor in HCC, neuroblastoma, leukemia, colon, and thyroid cancers." (PMID 24405831, 2014). "Malignant melanoma cell lines were treated with rWNT5A or WNT5A siRNA, and mRNA versus protein levels of soluble mediators were measured using RT-PCR, cytokine bead array and ELISA." (PMID 24766647, 2014). "It had previously been reported that WNT5A expression was connected to the presence of the immunomodulatory and pro-angiogenic factor IL-6 in supernatants from malignant melanoma cells." (PMID 24766647, 2014). "Due to the fact that IL-6 mRNA levels remained unaffected in our study we believe that the mechanism behind WNT5A induced IL-6 release in malignant melanoma cells is Myd88/TLR2 independent." (PMID 24766647, 2014). "We have previously shown that WNT5A induces an intracellular Ca2+-increase in human malignant melanoma and breast cancer cells." (PMID 24766647, 2014). "We and others have previously shown that WNT5A induces an intracellular calcium signal in melanoma cells and breast cells." (PMID 24766647, 2014). "In line with this, a high WNT5A expression was also correlated to a poor prognosis in melanoma patients." (PMID 24766647, 2014). "Actually, a potential association between PKC activation and Wnt5a expression was reported in human melanoma based on the observations that blocking the Wnt5a pathway using specific antibodies inhibited PKC activation, cell motility and invasion." (PMID 23349696, 2013). "In support of these findings, our group has shown that WNT‐5A can reverse the effect on WNT‐3A‐induced Topflash reporter activity in A2058 melanoma cells." (PMID 23727359, 2013). "It has been shown that Wnt5a stimulates migration and invasiveness in some cancer cells like melanoma, breast cancer, lung cancer and gastric cancer." (PMID 23844260, 2013). "Wnt5A activates calpain-1, leading to the cleavage of filamin A, which results in a remodeling of the cytoskeleton and an increase in melanoma cell motility." (PMID 23388158, 2013). "Our group previously reported constitutive Wnt5a expression in human pancreatic cancer and malignant melanoma cell lines and suggested the role of Wnt5a in growth and migration in both of these cancer cell lines." (PMID 23947922, 2013). "In melanomas and gastric and pancreatic carcinomas, WNT5A is recurrently overexpressed and exerts a pro-oncogenic function by promoting proliferation and/or invasion and metastasis." (PMID 24260410, 2013). "These Fzd receptor isoforms have also been shown to mediate Wnt5a-induced directional motility in melanoma, as well as invasive migration in breast cancer." (PMID 22384081, 2012). "Wnt5a actually promotes cancer progression and metastasis, such as malignant melanoma and gastric cancer." (PMID 22655072, 2012). "Wnt5a was able to polarise the cellular cytoskeleton of melanoma cells through a process dependent on dishevelled, RhoB and Rab4 to promote cellular migration towards the source of the CXCL12 chemokine." (PMID 22655072, 2012). "We next investigated if inhibition of Wnt5a signaling by SFRP3 was also the mechanism of the inhibition of migration observed by stimulation of melanoma cells with rSFRP3." (PMID 21494614, 2011). "Several groups have identified WNT5A as a key regulator of metastasis in melanoma, breast and gastric cancers." (PMID 22016777, 2011).
melanoma (continued). "Our assumption that SFRP3-mediated inhibition of Wnt5a is the mechanism by which it affects melanoma cell migration, readily explains the relatively small effect of SFRP3 on migration and invasion in A2058 cells with low expression of Wnt5a." (PMID 21494614, 2011). "Wnt5a signaling has been shown to increase the migration and invasion of malignant melanoma cells, and high expression of Wnt5a in melanoma tumors has been connected to a poor prognosis." (PMID 21494614, 2011). "Recent studies identified a modified Wnt5a-derived hexapeptide (Box5) that can specifically antagonize Wnt5a in malignant melanoma cells." (PMID 21857966, 2011). "Wnt5a signaling has been demonstrated to affect motility of melanoma whereas SFRP3 has been shown to reduce growth and motility in other types of cancer." (PMID 21494614, 2011). "We therefore conclude that the effects of SFRP3 on melanoma cell migration are due to impaired Wnt5a signaling, either via binding between the CRD of SFRPs to the CRD of the Wnt protein or its receptors, in accordance with previous findings in other systems." (PMID 21494614, 2011). "It has previously been shown that Wnt-5a is involved in the invasion of various cancers including melanoma, breast cancer, gastric cancer, pancreatic cancer and osteosarcoma." (PMID 21998657, 2011). "In majority of cases, Wnt5a signaling has opposite effects than Wnt/β-catenin signaling, for example in malignant melanoma." (PMID 22039506, 2011). "For example, in melanoma WNT5A promotes the metastatic potential of the cells, antagonizes Wnt/catenin signaling at later stages, and contributes to cell proliferation." (PMID 22073312, 2011). "We conclude that SFRP3 functions as a melanoma migration and invasion suppressor by interfering with Wnt5a signaling." (PMID 21494614, 2011). "To complement this finding, we investigated the effects of SFRP3 in the melanoma HTB63 cells which have a higher Wnt5a expression compared to A2058 cells." (PMID 21494614, 2011). "As the Wnt/Ca2+ pathway has been found to be important for the invasive capacities of Wnt5a in melanoma cells, we analyzed the effect of SFRP3 on Wnt5a induced intracellular calcium signaling." (PMID 21494614, 2011). "The notion that SFRP3 affects melanoma cell migration via modulation of Wnt5a signaling is supported by numerous studies on how Wnt5a regulates melanoma cell migration." (PMID 21494614, 2011). "Weeraratna and colleagues suggested that Wnt5A increased cell motility in human melanoma cell lines by activation of protein kinase C (PKC)." (PMID 20454608, 2010). "In vivo administration of a recombinant Wnt5A protein increased metastasis in a mouse model, further highlighting the potential role of this pathway in late-stage melanoma." (PMID 24281103, 2010). "Another group found an association between constitutive toll-like receptor 3 (TLR-3) activation and constitutive Wnt5A expression in melanoma cell lines." (PMID 24281103, 2010). "In contrast, WNT5A also has a tumour-promoting role in cases such as non-small-cell lung cancer, melanoma, breast, gastric, pancreatic and prostate cancers." (PMID 20591152, 2010). "Further studies from Weeraratna and colleagues revealed that Wnt5A can control cell polarity, orientation, and directional movement in melanoma cells." (PMID 24281103, 2010). "Antagonism of β-catenin due to overexpression of Wnt5A, leading to downregulation of Wnt/β-catenin target has been proposed previously in melanoma and Xenopus embryos." (PMID 20454608, 2010). "In this particular example, the use of the status of Wnt5a has resulted from prior biological knowledge relating the status of this gene to metastasis in melanoma tumors." (PMID 20436874, 2009). "The optimal and approximate intervention strategies are found for the melanoma-related context-sensitive PBN when different genes in the network (except WNT5A itself) are employed as the control genes." (PMID 19404383, 2009).
melanoma (continued). "Wnt5a has been described as a tumor promoter in melanoma, gastric, pancreas, prostate cancer, but as a tumor suppressor in HCC, neuroblastoma, leukemia, colon, and thyroid cancers." (PMID 19849855, 2009). "Recently, it was reported that WNT5a polarizes the cytoskeleton, allowing chemokine directed motility in melanoma cell lines." (PMID 19874621, 2009). "Nuclear β-catenin is lost in more aggressive melanomas that express Wnt5a that promotes EMT, cell motility and metastasis." (PMID 19849855, 2009). "A recent study provided further evidence of the opposing roles of different Wnts as β-catenin gene targets upregulated in B16 murine melanoma cells treated with Wnt-3a were universally downregulated in B16 cells treated with Wnt-5a." (PMID 19603030, 2009). "WNT5A, identified as a robust marker of highly invasive human melanoma cells was shown to mediate motility through activated classical PKCs." (PMID 18442364, 2008). "Of note, detection of WNT5A in the RGP library is in marked contrast to previous evidence that WNT5A is strongly associated with aggressiveness in human melanoma and also to a most recent finding that KISS1 expression is down-regulated by Wnt5a." (PMID 18211678, 2008). "Additionally, Wnt5a overexpression in melanoma cells activates PKC, upregulating MMP-2 and promoting cell spread." (PMID 40399946, 2025). "In melanoma, Wnt5a enhances APT1 activity through phosphorylation." (PMID 41306774, 2025). "Moreover, WNT5A has been proposed to control calcium‐dependent exosome release in malignant melanoma cells and through WNT5a/PI3K/miR‐122 in hepatocyte differentiation." (PMID 40165582, 2025). "HH044 treatment was shown to decrease WNT5A, likely decreasing the non-canonical signaling responsible for mediating the migration and motility of melanoma cells associated with metastasis." (PMID 40574005, 2025). "Wnt5a has been shown to act as a proto-oncogene in melanoma, breast cancer, prostate and pancreatic cancer, and a tumor suppressor in breast cancer, colon, thyroid and esophageal squamous cell carcinoma, acute lymphoblastic lymphoma, acute myeloid lymphoma, and neuroblastoma." (PMID 40028182, 2025). "Interestingly, WNT5a is overexpressed in a subset of cancers, such as melanoma, gastric, and pancreatic cancers, and, as a consequence, promotes tumor progression." (PMID 40165582, 2025). "Interestingly, compared with NHEMs, all our melanoma cell lines tended to exhibit reduced expression of Wnt5a." (PMID 38388496, 2024). "Moreover, in melanoma cells, Wnt5a stimulates exosomes to release their cargo, including immunomodulatory and pro-angiogenic proteins such as vascular endothelial growth factor and matrix metalloproteinase-2." (PMID 39850798, 2024). "However, fibroblasts undergo age-related reprogramming and release a soluble antagonist (sFRP1) of WNT5A, thus enabling metastatic outgrowth of melanoma metastases in mice." (PMID 38419052, 2024). "WNT5A inhibitors have been shown to effectively suppress melanoma cell invasion in vitro by blocking WNT5A signalling, and have been identified as potential therapeutic options for ovarian cancer, however, validation of their clinical utility in vivo is urgently required." (PMID 39164966, 2024). "Wnt5a is another important ligand that increases the invasiveness of melanoma cells." (PMID 38388496, 2024). "Previous studies showed that Melanoma-derived Wnt5a promotes the transcriptional expression of IDO1 in nearby DCs by Wnt5a-β-catenin signaling and activates the PPAR-γ signaling pathway, culminating in enhanced IDO1 activity to establish an immunosuppressive microenvironment." (PMID 39424786, 2024). "Similarly, human SDC4 favors cell migration and invasion through activation of Wnt5A signals in melanoma, indicating conserved signaling downstream of this proteoglycan in NC cell migration and malignant progression of an NC-derived cancer." (PMID 38634469, 2024).